RHOA (ras homolog family member A)
Diseases named in the same sentence as RHOA in open-access papers (continued):
Sharing a sentence is not in itself a finding about the gene and the disease.
asthma (35 papers, 2005 to 2025). "Increased activation of RhoA/Rho-kinase is associated with airway hyper-responsiveness and smooth muscle contraction in asthma." (PMID 36206293, 2022). "Inhibition of RhoA suppressed BaP and Der f 1 co-exposure-induced airway hyper-responsiveness, Th2-associated airway inflammation, and TGFβ1 signaling activation in asthma." (PMID 33936062, 2021). "Here, we report that RhoA in AT2 protects against allergen-induced airway inflammation in asthma and its underlying mechanisms." (PMID 34101619, 2021). "Recent advances have suggested that RhoA is associated not only with airway hyper‐responsiveness, but also with other key features of asthma, such as airway remodelling, allergic airway inflammation and airway barrier dysfunction." (PMID 32355562, 2020). "The RhoA/Rho kinase pathway is directly implicated in asthma, promoting bronchoconstriction, airway remodeling, and airway inflammation." (PMID 24637581, 2014). "Increased expression and activation of RhoA have been associated with asthma." (PMID 33936062, 2021). "RhoA‐deficient mice showed a significant reduction in CD4+ T cells and concomitant inhibition of Th2‐differentiation potential, as well as attenuated allergic airway inflammation, pointing out the critical role of RhoA in asthma development." (PMID 41065049, 2025). "The small GTPase RhoA and its downstream effectors are critical regulators in the pathophysiological processes of asthma and a promising therapeutic target for the treatment of asthma." (PMID 39100210, 2024). "In this section, we will focus on the role of ASM in asthma etiology due to altered RhoA/ROCK signaling that contributes to the muscle’s dysfunction, and more specifically, to the mechanical properties of ASM cytoskeleton." (PMID 38392332, 2024). "In an ovalbumin-sensitized rat model of asthma, it has been shown that the expressions of RhoA and ROCK mRNA and proteins are significantly increased." (PMID 38392332, 2024). "It is well-known that RhoA/ROCK is involved in the pathophysiology of asthma, especially in airway hyperresponsiveness, airway remodeling and pulmonary inflammation." (PMID 38392332, 2024). "In an antigen-challenged murine asthma model, lovastatin ameliorates bronchial smooth muscle hyperresponsiveness by reducing RhoA-mediated signaling, and it also reduces the expression of geranylgeranyltransferase I in bronchial smooth muscle." (PMID 37241840, 2023). "It has been reported that RhoA activation is increased in airway epithelial cells of mouse model of asthma." (PMID 36369000, 2022). "Upregulated expression and activation of RhoA have been associated with bronchial smooth muscle contraction, AHR, and airway remodeling in asthma." (PMID 34101619, 2021). "Results have shown that ezrin can contribute to asthma by affecting bronchial epithelium repair via RhoA pathways." (PMID 34065716, 2021). "Here, we found that RhoA in AT2 cells plays a critical role in regulating allergen-induced AHR and Th2-associated airway inflammation in allergen-induced mouse models of asthma." (PMID 34101619, 2021). "Increased activation of RhoA/Rho-kinase has been associated with bronchial smooth muscle contraction and AHR in asthma." (PMID 34101619, 2021). "We further confirmed the role of RhoA in TGFβ expression and signaling activation in the airway epithelium of an asthma mouse model by co-immunostaining with epithelial marker EpCAM." (PMID 33936062, 2021). "The small GTPase RhoA and its downstream effectors are critical regulators in the pathophysiological processes of asthma." (PMID 34101619, 2021). "It is well known that RhoA/Rho-kinases play an important role in the pathophysiology of asthma, including airway hyper-responsiveness and airway remodeling." (PMID 34065716, 2021). "We specifically investigated the role of RhoA in BaP co-exposure-induced AHR and allergic airway inflammation in asthma by using RhoA inhibitors Y-27632 and fasudil." (PMID 33936062, 2021).
asthma (continued). "Our previous studies found an increased expression of active RhoA in airways from patients with asthma, but its role in airway epithelial cells remains unexplored." (PMID 34101619, 2021). "For example, studies demonstrated an increased expression of RhoA in rats with airway remodelling in asthma." (PMID 32355562, 2020). "The present review demonstrates that RhoA/Rho‐kinase is substantially involved in the pathophysiological changes of asthma, including airway hyper‐responsiveness, airway remodelling and lung inflammation." (PMID 32355562, 2020). "Together, these studies suggested a positive loop between TGF‐β1 and RhoA/Rho‐kinase signalling that drives the airway hyper‐responsiveness in asthma." (PMID 32355562, 2020). "The ras homolog family member A (RhoA) of the Rho family GTPases has been considered to be one of the most promising and novel therapeutic targets for asthma." (PMID 32355562, 2020). "Collectively, these findings suggest that RhoA is a promising and novel therapeutic target for asthma." (PMID 32355562, 2020). "It is well known that RhoA/Rho‐kinases play an important role in the pathophysiology of asthma, including airway smooth muscle contraction, airway hyper‐responsiveness, β‐adrenergic desensitisation and airway remodelling." (PMID 32355562, 2020). "In this review, we evaluate the literature regarding the recent advances in the regulation of RhoA/Rho‐kinase activation and the role of RhoA/Rho‐kinase in regulating major features of asthma, such as airway hyper‐responsiveness, remodelling and inflammation." (PMID 32355562, 2020). "ARHGEF1, another RhoGEF, is an activator of RhoA increased in the airway smooth muscles from patients with asthma and in the lung tissues from OVA‐challenged mice." (PMID 32355562, 2020). "We evaluate recent advances in cytokine and epigenetic regulation of RhoA/Rho‐kinase and the role of RhoA/Rho‐kinase in regulating major clinical features of asthma, such as airway hyper‐responsiveness, remodelling and inflammation." (PMID 32355562, 2020). "With the combined use of conditional RhoA-deficient mice and fasudil, we found that RhoA orchestrated glycolysis for Th2 differentiation and OVA-induced asthma." (PMID 31623153, 2019). "In this animal model of asthma, an augmented RhoA-mediated Ca2+ sensitization of the BSM contraction is a cause of the BSM hyper-contractility." (PMID 30161143, 2018). "MiR-133a negatively regulates RhoA in bronchial smooth muscle cells (BSMCs), a new target for asthma therapy." (PMID 23878802, 2013). "The involvement of the small G protein RhoA in synergism induced by GPCR agonists and growth factors should also be considered, which is interesting given that RhoA expression is increased in animal models of asthma and COPD." (PMID 16684353, 2006). "RhoA is a critical player in the induction of allergic inflammation and asthma pathogenesis." (PMID 39712874, 2024). "We then explored whether the RhoA/ROCK1 signaling pathway was involved in GPR40-regulated asthma in obese mice." (PMID 36803977, 2023). "RhoA/ROCK1 pathway has been reported to link closely with AHR in asthma." (PMID 36803977, 2023). "Previous study has shown that overexpression of RhoA is involved in the pathogenesis of asthma." (PMID 36369000, 2022). "Anti-NGF improves AHR and relieves asthma attacks in mice by downregulating the RhoA pathway." (PMID 34502019, 2021). "Furthermore, the disruption of RhoA in T cells can also suppress Th17 responses and neutrophil-involved airway inflammation in an allergen-induced asthma model." (PMID 34101619, 2021). "Therefore, anti-NGF possibly improves AHR and relieves asthma attacks in mice via downregulating the RhoA pathway." (PMID 34502019, 2021). "To confirm whether the reduced Tgf-β1 was caused by the deletion of RhoA in AT2 cells of Sftpc-cre;RhoAfl/fl mice, we examined Tgf-β1 expression specifically in AT2 cells of the asthma mouse model by coimmunofluorescence staining with both Tgf-β1 and Sftpc." (PMID 34101619, 2021).
asthma (continued). "Importantly, several studies including ours have suggested a feed-forward circuit between RhoA signaling and TGFβ1 that drives airway constriction, airway hyper-responsiveness, and airway remodeling in asthma." (PMID 33936062, 2021). "Furthermore, we found a co-localization between AhR and RhoA-GTP in the airways of an asthma mouse model, indicating a possible interaction between AhR and RhoA-GTP." (PMID 33936062, 2021). "AT2 cell–specific deletion of RhoA leads to changes in cytokine release of asthma mouse models." (PMID 34101619, 2021). "Our further study revealed that inhibition of RhoA/Rho-kinase signaling significantly suppressed BaP co-exposure-induced AHR, Th2-associated airway inflammation, and airway epithelial cytokine release in a mouse model of asthma." (PMID 33936062, 2021). "Taken together, these findings indicate that RhoA/Rho‐kinase signalling shows promise for AHR, suggesting that RhoA/Rho‐kinase may be a potential therapeutic target for severe asthma." (PMID 32355562, 2020). "Furthermore, disruption of RhoA in T cells markedly suppressed Th17 response and neutrophil‐involved airway inflammation in an allergen‐induced asthma model." (PMID 32355562, 2020). "We also asked the question whether RhoA signalling is involved in cockroach allergen‐induced airway remodelling in our well‐established chronic mouse model of asthma." (PMID 32355562, 2020). "Importantly, the development of new, safe, more specific and potent inhibitors targeting RhoA/Rho‐kinase is crucial for the treatment of asthma in the future." (PMID 32355562, 2020). "Indeed, RhoA/Rho‐kinase‐mediated Ca2+ sensitisation is markedly enhanced in experimental asthma and involved in bronchial smooth muscle (BSM) hyper‐responsiveness." (PMID 32355562, 2020). "We suggest that RhoA/Rho‐kinase signalling may be a promising therapeutic target for the treatment of asthma." (PMID 32355562, 2020). "Similarly, TNF‐α also increased RhoA expression and via NF‐κβ binding elements, leading to bronchial hyper‐responsiveness in asthma." (PMID 32355562, 2020). "Collectively, these findings reveal that miRNAs may be therapeutic candidates for asthma by targeting RhoA/Rho‐kinase signalling." (PMID 32355562, 2020). "Of interest, the increased expression of a‐SMA was blocked by Y‐27632, indicating that RhoA signalling may be involved in SPC‐induced airway remodelling in asthma." (PMID 32355562, 2020). "Especially, RhoA/Rho‐kinase is involved in regulating airway inflammation through affecting migration, differentiation and function of various inflammatory cells (e.g. eosinophils, macrophages, mast cells and T cells) in the pathogenesis of asthma." (PMID 32355562, 2020). "The RhoA/Rhokinase pathway has now been proposed as a new target for the treatment of AHR in asthma and modulation of this pathway by miR-133a might provide a new insight into the treatment of AHR." (PMID 23878802, 2013). "Other papers present original research that advances our understanding of the roles of adiponectin and RhoA proteins in asthma, which may serve as novel targets for asthma treatment in the future." (PMID 24294267, 2013). "However, whether GRP40 regulates AHR in obese asthma through RhoA/ROCK1 signal pathway remains elusive." (PMID 36803977, 2023). "Thus, RhoA has been considered as a novel target molecule for the treatment of asthma." (PMID 34101619, 2021). "This validates Fructus Xanthii’s role in blocking NF-κB/MAPK cascades, inhibiting extracellular HSP90α-mediated RhoA/MLC signaling, and preserving epithelial barrier integrity, as extracellular HSP90α exacerbates bronchial dysfunction in asthma." (PMID 41403444, 2025). "Increased protein expression of RhoA, ROCK, MLC20, and MLCK has also been found in the lungs of a murine model of asthma." (PMID 38392332, 2024). "Previous studies demonstrated that deleting RhoA in AT2 cells exacerbated airway hyperresponsiveness and inflammation through SLC26A4 in a murine asthma model." (PMID 39712874, 2024).
asthma (continued). "MFG‐E8 has been shown to be reduced in an OVA‐induced asthma model and plays a role in suppressing inflammation and airway hyper‐responsiveness that are primarily the result of MFG‐E8 effects on RhoA and PTEN pathways in smooth muscle cells." (PMID 36840485, 2023). "RhoA (a RAS analog) is involved in the pathogenesis of allergic diseases, such as asthma, allergic rhinitis and dermatitis." (PMID 35910793, 2022). "Our IHC staining showed that RhoA expression was elevated in OVA-challenged mice, indicating the involvement of RhoA in asthma pathogenesis." (PMID 36369000, 2022). "TNF-α, IL-13, IL-4, IL-17A and CCL2 are found to increase RhoA mRNA expression via NF-κβ and STAT6 signaling pathways activation, leading to airway hyperreactivity in asthma." (PMID 34069141, 2021). "Collectively, these studies highlight a critical role for the activated RhoA signaling in AT2 cells in allergic airway inflammation and provide a potential therapeutic effect of anti–RhoA-SLC26A4 approaches in patients with asthma." (PMID 34101619, 2021). "Importantly, we made novel findings that BaP-activated AhR can bind to the promoter region of RhoA and regulate RhoA/Rho-kinase activation, and inhibition of RhoA significantly suppresses co-exposure-induced AHR, Th2-associated airway inflammation, and TGFβ1 signaling in a mouse model of asthma." (PMID 33936062, 2021). "Of interest, a feed-forward connection between RhoA signaling and TGF-β1 has been suggested to drive airway constriction and AHR in asthma." (PMID 34101619, 2021). "Further mechanistic studies suggest that TSG12, a TG2 agonist, relaxed airway smooth muscles and reduced asthmatic pulmonary resistance through RhoA phosphorylation in both OVA‐ and HDM‐induced mouse models of asthma." (PMID 32355562, 2020). "To our knowledge, we provide the first evidence on the role of caveolin-1/VEGFR2 on VEGF-induced RhoA activation and MUC5AC upregulation in bronchial epithelial cells, suggesting an effective therapeutic target in inflammatory diseases such as asthma." (PMID 31831011, 2019). "Y27632, another RhoA-ROCK inhibitor, can suppress ovalbumin (OVA)-induced murine asthma with reduced IL-17 mRNA expression in lungs." (PMID 31623153, 2019). "The eHsp90α mediates HDM-induced human bronchial epithelial barrier dysfunction by activating RhoA/MLC signaling, suggesting that eHsp90α is a potential therapeutic target for treatment of asthma." (PMID 28558721, 2017). "RhoA/ROCK1 signal pathway has been reported to serve as a proximal downstream effector of numerous GPCRs, and plays an important role in the pathophysiology of asthma, including airway smooth muscle contraction, AHR, and airway remodeling." (PMID 36803977, 2023). "Interlukin-13-dependent RhoA protein expression is negatively controlled by miR-140-3p in ASMs, according to a study, and the RhoA/Rho-kinase pathway has been suggested as a new target for the therapy of AHR in asthma." (PMID 36459329, 2022). "To determine whether RhoA controls cytokine release in airway epithelial cells, we detected several major epithelial cell–derived cytokines in the BALF of asthma mouse models." (PMID 34101619, 2021). "Thrombin induces the doublecortin like kinase 1/Ras homolog gene family, member A (RhoA) signaling pathway, activating YAP and forming YAP/p65, which enhances IL‐8/chemokine (C–X–C motif) ligand 8 (CXCL8) expression through NF‐κB binding, contributing to asthma development." (PMID 40066231, 2025). "The decreasing miR-133a could up-regulate RhoA expression of bronchial smooth muscle in an asthma model, which may lead to an augmentation of bronchial smooth muscle contraction and induce airway hyperresponsiveness (AHR) in individuals with asthma." (PMID 36002808, 2022). "In addition, VEGF participates in airway smooth muscle remodeling and can induce an asthma-like phenotype, but the RhoA/ROCK pathway may not be the only signaling pathway, and other signaling pathways or targets need further study." (PMID 38093231, 2023).
asthma (continued). "Although the mechanism(s) of up-regulation of RhoA in OA-challenged BSMs is not known here, inflammatory cytokines such as tumor necrosis factor-α, which is also demonstrated in airways of this murine model of asthma (unpublished data), may be involved in." (PMID 15638941, 2005).